MNAT1 (MNAT1 component of CDK activating kinase)
Description:
Component of the CDK-activating kinase (CAK) complex, a master regulator of CDK activity by catalyzing the activating threonine phosphorylation of CDKs. Binds and activates CDK7, the catalytic subunit of CAK. CAK activates major mediators of cell cycle control, including CDK1, CDK2, CDK4 and CDK6, and plays a key role in regulating cell cycle progression. CAK complexed to the core-TFIIH basal transcription factor activates RNA polymerase II by serine phosphorylation of the repetitive C-terminal domain (CTD) of its large subunit (POLR2A), allowing its escape from the promoter and elongation of the transcripts. Involved in cell cycle control and in RNA transcription by RNA polymerase II.
Synonyms: CAP35; MAT1; RNF66; TFB3
Tractability: Small molecule: a structure with a bound ligand is known; a high-quality ligand is known. PROTAC: ubiquitination databases record sites on it; its protein half-life has been measured.
Gene: Protein-coding gene on chromosome 14 (60,734,742 to 60,969,965, forward strand). Ensembl gene ENSG00000020426.
Subcellular location: Nucleus
Subcellular location (Human Protein Atlas): Nucleoplasm
Pathways (Reactome):
Gene expression (Transcription): Formation of RNA Pol II elongation complex; Formation of the Early Elongation Complex; NoRC negatively regulates rRNA expression; RNA Pol II CTD phosphorylation and interaction with CE; RNA Polymerase I Promoter Escape; RNA Polymerase I Transcription Initiation; RNA Polymerase I Transcription Termination; RNA Polymerase II Pre-transcription Events; RNA Polymerase II Promoter Escape; RNA Polymerase II Transcription Elongation; RNA Polymerase II Transcription Initiation; RNA Polymerase II Transcription Initiation And Promoter Clearance; RNA Polymerase II Transcription Pre-Initiation And Promoter Opening; RUNX1 regulates transcription of genes involved in differentiation of HSCs
Disease: Formation of HIV elongation complex in the absence of HIV Tat; Formation of HIV-1 elongation complex containing HIV-1 Tat; Formation of the HIV-1 Early Elongation Complex; HIV Transcription Initiation; RNA Pol II CTD phosphorylation and interaction with CE during HIV infection; RNA Polymerase II HIV Promoter Escape; Tat-mediated elongation of the HIV-1 transcript; Transcription of the HIV genome
DNA Repair: Dual incision in TC-NER; Formation of Incision Complex in GG-NER; Formation of TC-NER Pre-Incision Complex; Gap-filling DNA repair synthesis and ligation in TC-NER; Transcription-Coupled Nucleotide Excision Repair (TC-NER)
Cell Cycle: Cyclin A/B1/B2 associated events during G2/M transition; Cyclin A:Cdk2-associated events at S phase entry; Cyclin D associated events in G1; Cyclin E associated events during G1/S transition
Metabolism of RNA: mRNA Capping
Gene Ontology:
Molecular function: protein binding; zinc ion binding; cyclin-dependent protein serine/threonine kinase activator activity
Biological process: regulation of G1/S transition of mitotic cell cycle; regulation of transcription by RNA polymerase II; transcription initiation at RNA polymerase II promoter; DNA repair; nucleotide-excision repair; G1/S transition of mitotic cell cycle; negative regulation of apoptotic process; positive regulation of smooth muscle cell proliferation
Cellular component: CAK-ERCC2 complex; cyclin-dependent protein kinase holoenzyme complex; nucleoplasm; transcription factor TFIIH core complex; transcription factor TFIIH holo complex; transcription factor TFIIK complex; nucleus
Genetic constraint (gnomAD): Loss-of-function variants: 30 observed, 31.67 expected, observed/expected ratio (o/e) 0.95, 90% interval 0.71 to 1.28. The upper end of that interval is the gene's LOEUF score, 1.28, which puts it in group 5 of 6, group 1 being the genes least tolerant of losing a copy. Missense variants: 240 observed, 297.31 expected, observed/expected ratio (o/e) 0.81, 90% interval 0.73 to 0.9. Synonymous variants: 99 observed, 103.2 expected, observed/expected ratio (o/e) 0.96, 90% interval 0.81 to 1.13.
Homologues: Orthologues: chimpanzee MNAT1 (100% identical), macaque MNAT1 (100% identical), pig MNAT1 (98% identical), rabbit MNAT1 (98% identical), dog MNAT1 (97% identical), guinea pig MNAT1 (96% identical), rat Mnat1 (96% identical), mouse Mnat1 (95% identical), tropical clawed frog mnat1 (81% identical), zebrafish mnat1 (75% identical), Drosophila melanogaster Mat1 (54% identical), Caenorhabditis elegans mnat-1 (33% identical).
Diseases named in the same sentence as MNAT1 in open-access papers:
MNAT1 is named in the same sentence as 19 diseases in open-access papers, as found by Europe PMC text mining. Sharing a sentence is not in itself a finding about the gene and the disease. The quoted sentences say what the papers report.
colorectal cancer (5 papers, 2018 to 2021). A primary or metastatic malignant neoplasm that affects the colon or rectum. "Abnormal up-regulation of MNAT1 has been observed in breast cancer and colorectal cancer in recent studies and is associated with rapid cancer malignance and poor prognosis." (PMID 32453410, 2020). "MNAT1 was correlated with poor prognosis of several types of cancer including breast cancer, gastric cancer and colorectal cancer." (PMID 30243023, 2018). "In addition, MNAT1 has also been found to play important roles in pathogenesis of breast cancer and colorectal cancer." (PMID 32453410, 2020).
osteosarcoma (4 papers, 2020 to 2025). A usually aggressive malignant bone-forming mesenchymal neoplasm, predominantly affecting adolescents and young adults. "The depletion of has-circ-0001146 as well as the increase of miR-26a-5p decreased MNAT1 expression in osteosarcoma cells, while the reduction of miR-26a-5p was associated with increased MNAT1 expression." (PMID 32453410, 2020). "Emerging evidence indicates that MNAT1 promotes osteosarcoma pulmonary metastasis via AKT1 upregulation." (PMID 41235252, 2025). "While the expression patterns, functional significance, and underlying mechanisms of MNAT1 remain entirely unexplored in OSCC, it has been demonstrated to promote proliferation and cisplatin resistance in osteosarcoma by modulating the PI3K/Akt/mTOR pathway." (PMID 41235252, 2025). "It has been shown that there were MNAT1 upregulations in osteosarcoma tissues that were correlated with poor prognosis." (PMID 37303943, 2021). "The effects of the has-circ-0001146/miR26a-5p/Mnat1 network on the proliferation and invasion of osteosarcoma were evaluated by cell viability, apoptosis, migration, and invasion assays." (PMID 32453410, 2020). "Recent literature has documented that MNAT1 serves as a promoter to malignant behavior and lung metastasis of osteosarcoma." (PMID 33272245, 2020). "Bioinformatics analysis showed that has-circ-0001146 and miR-26a-5p were involved in the regulation of MNAT1 in osteosarcoma." (PMID 32453410, 2020). "The depletion of has-circ-0001146 or MNAT1 or the increase of miR-26a-5p inhibited osteosarcoma cell viability and invasion, and increased apoptosis." (PMID 32453410, 2020). "Osteosarcoma tissues showed higher MNAT1 and has-circ-0001146 expression than adjacent normal tissues, although the expression of MNAT1 was not significantly up-regulated in sarcomas according to TCGA databases." (PMID 32453410, 2020). "The present study confirmed that has-circ-0001146 blocked miR-26a-5p targeting MNAT1 in osteosarcoma cells, thereby promoting the malignant behaviours of osteosarcoma cells." (PMID 32453410, 2020). "MNAT1 downregulation suppressed osteosarcoma cell proliferation, invasion, and in-vivo growth." (PMID 37303943, 2021). "In OS, MNAT1 play an important role in the lung metastasis of osteosarcoma." (PMID 33272245, 2020). "MNAT1 promotes the malignant behaviors of osteosarcoma cells." (PMID 33272245, 2020).
breast carcinoma (3 papers, 2018 to 2020). "In breast cancer, expression of MNAT1 is bad expectations in Estrogen Receptor-Positive Breast Cancer." (PMID 33272245, 2020). "Moreover, in breast cancer, elevated expression of MNAT1 predicted poor prognosis and served as an oncogene." (PMID 33272245, 2020).
sarcoma (2 papers, 2020 to 2022). A usually aggressive malignant neoplasm of the soft tissue or bone. "The MNAT1 protein (menage a trois 1, MAT1) is upregulated in different sarcomas (Ewing’s sarcoma, synovial sarcoma), but in particular in OS tissues compared to normal bone tissue." (PMID 36672544, 2022).
head and neck cancer (1 paper, 2024). A primary or metastatic malignant neoplasm affecting the head and neck. "The single nucleotide polymorphism (SNP) of MNAT1 (rs12888332) was a significant predictor of recurrence of head and neck cancer." (PMID 38556856, 2024).
neuroblastoma (1 paper, 2025). Neuroblastoma (NB) is the most common solid, extracranial childhood tumor. "In contrast, MNAT1 showed a significant increase in inclusion in motor neurons and cortical neurons, with no such change observed in neuroblastoma cell lines." (PMID 40670663, 2025). "In support of this observation, neuroblastoma cell lines lacking cryptic exon inclusion exhibited no change in MNAT1 expression, effectively serving as a negative control." (PMID 40670663, 2025).
pancreatic cancer (1 paper, 2024). "This SMYD2-mediated MNAT1 upregulation activates the phosphoinositide 3-kinase (PI3K)/AKT serine/threonine kinase (AKT) pathway, leading to increased proliferation of pancreatic cancer cells." (PMID 39482529, 2024). "In pancreatic cancer, SMYD2 was found to be overexpressed, and SMYD2 upregulated the MNAT1 component of CDK-activating kinase (MNAT1), which is a component of cyclin-dependent kinase (CDK)-activating kinase, via H3K36me2 modification in the promoter region." (PMID 39482529, 2024).
proteinopathy (1 paper, 2025). "We developed IsoRefiner to identify full-length transcripts via long-read RNA-seq and found a cryptic exon in the MNAT1 gene in ALS and FTD patients, suggesting its role in TDP-43 proteinopathy." (PMID 40670663, 2025).
cancer (5 papers, 2018 to 2024). A tumor composed of atypical neoplastic, often pleomorphic cells that invade other tissues. "CDKN3, CKS2 and MNAT1 consist of serine/threonine kinases crucial for regulating cell cycle transition and are significantly implicated in the pathogenesis of numerous cancers." (PMID 39689117, 2024). "MNAT1 is highly expressed in various types of cancer and is involved in the molecular pathogenesis of cancer and drug resistance." (PMID 38026933, 2023). "Mounting evidence has revealed that MNAT1 play a pivotal part in regulation of biological characteristics of cancer cells." (PMID 33272245, 2020). "Since the present study identified the existence of the has-circ-0001146/miR26a-5p/Mnat1 network in OS, the cancer promoting effect of has-circ-0001146 in OS is potentially associated with the interference of miR26a-5p targeting Mnat1." (PMID 32453410, 2020). "In this research, we revealed that MNAT1 was upregulated in OS cancer tissues and cell lines." (PMID 33272245, 2020).
tumor (4 papers, 2020 to 2025). "Mechanistically, MNAT1 coordinates with tumor-associated macrophages through the MIF and IFN-II signaling axis, synergistically driving OSCC progression via immune microenvironment remodeling." (PMID 41235252, 2025). "Given hsa-circ-0001146 was implicated in MNAT1 expression, the present study stably knocked down hsa-circ-0001146 expression in 143B cells to determine the effects on MNAT1 tumor-promoting actions in vivo." (PMID 32453410, 2020). "Strikingly, macrophages co-cultured with MNAT1-knockdown tumor cells showed reduced expression of the M2 markers CD206 and CD163, indicating that MNAT1 knockdown suppresses M2 polarization of macrophages, thereby impeding tumor progression." (PMID 41235252, 2025). "Consistently, MNAT1 exhibited significant upregulation in tumor tissues compared to normal counterparts." (PMID 41235252, 2025). "Our previous study demonstrated that overexpression of MNAT1 promoted xenograft tumor growth and metastasis to lung tissues." (PMID 32453410, 2020). "More importantly, the high level of MNAT1 generally indicates the high metastasis of tumor, vascular invasion and advanced TNM stage." (PMID 33272245, 2020). "Through literature review, we found that MNAT1 plays an important role in tumor development." (PMID 41235252, 2025). "Moreover, knockdown of MNAT1 markedly reduced the tumor volume, with a much lower tumor tissue weight." (PMID 33272245, 2020). "In addition, downregulation of MNAT1 inhibited OS cell proliferation and invasion ability in vitro, suppressed and slowed down tumor growth in vivo." (PMID 33272245, 2020). "Functional studies had shown that MNAT1 silencing could weaken the invasion, migration and proliferation of OS cells in vitro, and inhibit OS tumor growth in vivo." (PMID 33272245, 2020). "Additionally, IHC staining showed that expression of PI3K, AKT and mTOR was decreased in the MNAT1-knockdown xenograft tumor tissues." (PMID 33272245, 2020). "In addition, IHC staining revealed that the relative expression of MNAT1 and proliferation marker Ki-67 were remarkably weaker in the tumor from MNAT1 knockdown group." (PMID 33272245, 2020). "Our results suggest that MNAT1, EIF3F, and PSMD10 are all highly expressed in the low differentiation state, indicating these key genes are critical factors promoting tumor malignancy." (PMID 41235252, 2025). "In pooled differential expression analyses between healthy and tumor samples more proteins were downregulated, while several proliferation-related proteins (e.g., POL2RK, MEN1, MNAT1, TAF9, or SDHC) and biological processes were upregulated." (PMID 38802361, 2024). "Simultaneously, we uncovered that mRNA levels of MNAT1 were up-regulated in 30-paired OS cases and surrounding tissue not invaded by the tumor (non-tumor tissue)." (PMID 33272245, 2020). "In addition, MNAT1 expression was remarkably higher in OS tumor tissue in situ than that in surrounding non-tumor tissues." (PMID 33272245, 2020).
MNAT1 also shares sentences with these, for which no sentence is quoted: preeclampsia (2 papers); cervical carcinoma (1); diffuse large B-cell lymphoma (1); gastric cancer (1); lung squamous cell carcinoma (1); lymphoid neoplasm (1); ovarian carcinoma (1); pancreatic adenocarcinoma (1); Thrombocytopenia (1).